PAK4 (p21 (RAC1) activated kinase 4)
Diseases named in the same sentence as PAK4 in open-access papers (continued):
Sharing a sentence is not in itself a finding about the gene and the disease.
cancer (continued). "Both PAK4 and PHF8 have roles in the regulation of various cellular processes that are involved in cancer progression, including cell proliferation, survival from apoptosis, migration, angiogenesis, metabolic regulation, and immune evasion of cancer cells." (PMID 36980457, 2023). "Therefore, based on the oncogenic roles of PAK4 and PHF8, variable strategies to inhibit them have been evaluated in various cancers." (PMID 36980457, 2023). "PAK4 bind to p85, the regulatory subunit of PI3K, which in turn increases the activity of PI3K and phosphorylation of AKT, thereby promoting the migration of cancer cells." (PMID 36672500, 2023). "The subcellular distribution of PAK4 and PHF8 expression in carcinoma tissue from human gallbladders differed between cases, with some cases having expression primarily in the cytoplasm, others in the nuclei, and some in both the nuclei and cytoplasm of tumor cells." (PMID 36980457, 2023). "To elucidate how the lack of tumor PAK4 expression sensitizes cancer cells to anti-PD-1 immunotherapy, we aimed to characterize the tumor immune cell compartment." (PMID 36588582, 2022). "PAK1, PAK2, and PAK4 have a higher expression level in most of cancer types, while other PAKs are not." (PMID 33796531, 2021). "The expression of p21-activated kinase 4 (PAK4) is correlated with infiltration of T cells and DCs, which may mediate resistance to cancer immunotherapy." (PMID 32850400, 2020). "The group of mice injected with PAK4-Lv, but not control group, exhibited metastasis of cancer cells to the bones as measured by bioluminescence imaging (BLI) to quantify the photon flux." (PMID 30177834, 2019). "Taken together, this study suggest that abnormal levels of PAK4 will be an important strategy for cancer cells to avoid the negative effects of TGFβ on cell growth and thus indirectly enhance tumor metastasis under TGFβ signaling." (PMID 31435524, 2019). "PAK4 controls cell proliferation, survival, invasion, metastasis, the epithelial–mesenchymal transition (EMT), and drug resistance in vitro and in vivo, thereby promoting overall cancer progression." (PMID 30755582, 2019). "On the other hand, looking at studies on cancer stem cells, one could agree that p21 plays an important role in inducing stemness, especially through p21 activated kinases (PAK1, PAK3, and PAK4)." (PMID 31416295, 2019). "Previous studies hypothesize that under hypoxic conditions, PAK4 interacts with the Rho family GTPases to regulate the actin cytoskeleton and control AKT-mTOR-4E-BP1 signaling in cancers." (PMID 31795447, 2019). "Indeed, silencing of CCAT1 led to downregulation of many genes involved in cancer cell proliferation, survival and metastasis, such as EGFR, CDK4, YES1, PAK4, and HMGA1." (PMID 30190462, 2018). "For this reason, inhibitors that can reduce PAK4 protein and not just the kinase activity are needed in order to more efficiently block PAK4 in cancer." (PMID 28198380, 2017). "Unlike PAK4, the deletion of PAK7 is not sufficient to induce tumours in mice; however, PAK7 driver mutations have been described in cancers." (PMID 25366420, 2015). "PAK4 expression was detected both in the membranes and cytoplasm of NSCLC cancer cells in vivo." (PMID 25975262, 2015). "Therefore, subcellular localization of the expression of PAK4 and PHF8 might be different according to the type of cancer and biological status of cancer cells." (PMID 36980457, 2023). "However, despite this variable expression pattern, a higher expression of PAK4 and PHF8 might be used as a prognostic indicator for cancer patients." (PMID 36980457, 2023). "Thus, these phosphorylation modifications of NPF and regulatory factors that can phosphorylate NPF, such as Shp1, Dyrk1A, Casein Kinase II, PAK4, SRC, ERK, Abl, Cdk5, etc., may provide targets for anti-invasive cancer therapy." (PMID 37026902, 2023).
cancer (continued). "Noteworthy, PAK4 and the p85 α-subunit of PI3K specifically interact and the development of specific inhibitors able to dissociate PI3K from PAK4 represent a novel therapeutic approach in several types of cancers in which PI3K and PAK4 play a central role in tumor progression." (PMID 32471307, 2020). "Importantly, normal primary HMECs, expressing low PAK4 levels, did not undergo senescence upon PAK4 knockdown, indicating the possibility of selective targeting of cancer cells." (PMID 32158912, 2020). "The phosphorylation of Ser181 residue of PAK4 was observed in mitosis, in human kinome analysis, in TCR signaling analysis, in human embryonic stem cells differentiation, in human cancer cells and human liver phospho-proteomic analysis, as well as in the analysis of 14-3-3 interactome." (PMID 32471307, 2020). "However, not all of the cancer cell lines described here were responsive to KPT-8752 or KPT-9274 despite their having high levels of PAK4." (PMID 28198380, 2017). "However, the relationship between PAK4 and glucose metabolism in cancer cells has not been explored." (PMID 28542136, 2017). "However, the expression of other T-cell inhibitory receptors, such as Tim-3 (Havcr2) or Lag-3, and the cancer immune evasion-related factor Pak4 remained unchanged in MUP-uPA mice, regardless of the type of diet fed in parallel to the unchanged expression of indoleamine 2,3-dioxygenase (Ido1)." (PMID 34439245, 2021). "However, as PAK4 overexpression exists in multiple lines of cancer cells, whether such effect appears non-specific to various cancer cells needs further explored." (PMID 27919028, 2014).
tumor (135 papers, 2007 to 2025). "In this study, we demonstrate that knockout of PAK1 and PAK4 reprograms the immune microenvironment by promoting the activation and infiltration of immune cells, a process associated with normalisation of tumour vasculature." (PMID 40943273, 2025). "This molecular profile is consistent with the observed increase in angiogenesis and vessel calibre in PAK4KO tumours, suggesting that the PAK4 knockout enhanced VEGF-associated signalling, despite a reduced VEGFA expression in these cells." (PMID 41294859, 2025). "The staining intensity of PAK4 showed a significant association with more advanced category T (P = 0.018) and was notably elevated in patients with larger primary tumour volumes." (PMID 38890401, 2024). "After correcting for tumour stage, grade, and resection status, high PAK4 expression was noted to be associated with worse outcomes which is the opposite of a previous report." (PMID 38797819, 2024). "PAK4 inhibitor significantly attenuated tumour growth in mouse and was associated with increased proportions of IFN-γ-producing CD8+ T-cells." (PMID 38890401, 2024). "The expression of PAK4 increases with disease progression in several types of tumours, including HNSCC, and is associated with the aggressiveness of disease and poor prognosis." (PMID 38890401, 2024). "It has been demonstrated that PAK4 inhibition transformed the disordered morphology of the tumour-associated vasculature, characterised by tortuous and disjointed vessels with spatial heterogeneity, into a well-organised structure marked by continuous vessels." (PMID 38067120, 2023). "On the contrary, an increased cyclin-dependent kinase 5 (CDK5) regulatory subunit-associated protein 3 in HCC accelerated tumor metastasis bound to and activated PAK4." (PMID 36672500, 2023). "We expect high expression of PAK4 to indicate poor patient prognosis in tumor cases, but in PC and EC, contrary to most findings, low PAK4 expression seems to be closely linked with poor prognosis." (PMID 35800076, 2022). "Nevertheless, whilst the association between PAK4 and the tumor microenvironment is evident, further studies are needed to elucidate the key changes that facilitate the infiltration of immune cells and overcome the resistance to ICB." (PMID 36588582, 2022). "Further, PAK4 regulates the ratio of M1/M2 tumor-associated macrophages (TAM) through HSPH1, and PAK1 regulates chemotaxis and crawling along the tumor microvessel through LIMK1/Cofilin in neutrophils." (PMID 36230657, 2022). "PAK4 deficiency in endothelial cells mediated reconditioning of the tumor microenvironment, normalization of the tumor vasculature, and improvement of T cell migration into tumors." (PMID 35203517, 2022). "Moreover, we also investigated into the association of Pak4 with tumor immune infiltration and T cell exhaustion using TIMER database." (PMID 38807162, 2024). "Double knock out of PAK1 and PAK4 caused complete regression of tumour in a syngeneic mouse model." (PMID 38797819, 2024). "PAK4 influences genes linked to stem cell traits, affecting tumour sphere formation through STAT3." (PMID 38067120, 2023). "Because of its role in cytoskeleton organization, PAK4 loss might affect how cells interact with each other, which could impact the extracellular matrix, and hence, the tumor microenvironment." (PMID 36588582, 2022). "CREB may be less potent than PAK4 because the role of CREB is more restricted compared with PAK4, but it may specifically enhance the expression of Bcl‐2 with a reduced risk of tumour formation." (PMID 33615605, 2021). "Both inhibitors dampen PAK4 activity, thereby mitigating molecular signaling implicated in the cell cycle and metastatic progression, downregulating pivotal signaling pathways involved in tumorigenesis and progression, and consequently fostering potent anti-tumor and metastatic attributes." (PMID 40332759, 2025). "Moreover, PAK4 amplification is associated with poor prognosis in Ras-driven tumour models." (PMID 35969127, 2022).
tumor (continued). "Knockout of PAK1 or PAK4 inhibited angiogenesis within the tumour by decreasing the intra-tumoral expression of CD31 and CD34, two common endothelial cell markers responsible for angiogenesis." (PMID 40943273, 2025). "Together, these results suggested that PAK1 and PAK4 differentially affected angiogenesis and tumour vasculature, leading to a differential impact on the effect of gemcitabine in this immunocompromised SCID mouse model." (PMID 41228228, 2025). "PAK4 normally stabilizes β-catenin to suppress T-cell infiltration; thus, selectively inhibiting PAK4 normalizes the tumor vascular network and facilitates the influx of CD8+ T cells, sensitizing resistant TNBC tumors to PD-1 blockade." (PMID 41516322, 2025). "Preclinical studies have demonstrated that PAK selective inhibitors for PAK1 (FRAX597) and PAK4 (PF-3758309) suppress tumour growth and improve chemotherapy response across multiple solid tumours." (PMID 41228228, 2025). "The data from the analysis of the proteomic profiles of PAK1KO and PAK4KO tumours have revealed that knockout of PAK1 or PAK4 upregulated ICAM-1, MHC class I molecules and enriched the expression of proteins involved in leukocyte trans-endothelial migration." (PMID 40943273, 2025). "For instance, targeting PAK4 normalises the tumour vascular microenvironment and improves CAR-T immunotherapy for glioblastoma." (PMID 41294859, 2025). "In this study, we used immunocompromised mice models to investigate how knockout PAK1 and/or PAK4 change the structure and function of tumour blood vessels and how these changes affect chemotherapy outcomes." (PMID 41228228, 2025). "The fact that knockout of PAK1 or PAK4 reduced tumour vascularisation, thus vascular regression, while enhancing vasculature normalisation, indicates a key role of PAK1 or PAK4 in balancing vascular regression and normalisation." (PMID 40943273, 2025). "We have recently reported that knockout of PAK1 or PAK4 enhanced vascular normalisation, stimulating anti-tumour immunity against PC in an immunocompetent syngeneic mouse model." (PMID 41228228, 2025). "We investigated the effect of PAK4 on the MHC I expression of PDA cells and its relation to autophagy to reveal the mechanism(s) involved in anti-tumor immunity stimulated by PAK4 inhibition." (PMID 39941877, 2025). "Future work in immune-competent and orthotopic humanised models will be critical to determine how PAK1- or PAK4-targeted interventions can affect the tumour vasculature, immune infiltration, and chemotherapy response in a clinically meaningful context." (PMID 41294859, 2025). "Inhibition of PAK1 or PAK4 enhances T cell activation in PC by stimulating anti-tumour immunity through downregulation of PD-L1." (PMID 41228228, 2025). "We and others have demonstrated that the inhibition of PAK4 via knockout or small-molecular inhibitors, stimulates the cytotoxic T cells in tumor tissues to enhance the antitumor immunity." (PMID 39941877, 2025). "Antoni Ribas reported that in mouse tumor models, PAK4 gene knockout improved the response to PD-1 blockade therapy and enhanced antitumor effects." (PMID 40180890, 2025). "This study aims to investigate the effects of PAK1 and PAK4 on tumour vasculature, immune cell infiltration, and the connection between using PAK1-knockout (KO), PAK4 KO, and wild-type (WT) PDA cells in cell-based and mouse experiments." (PMID 40943273, 2025). "Given the established involvement of PAK signalling in angiogenesis and immune regulation, we have further determined the effects of PAK1 and PAK4 on tumour vasculature in PDA, and their impact on therapeutic outcomes." (PMID 41228228, 2025). "PF-3758309, a pyrrolopyrimidine-based inhibitor of p21-activated kinase 4 (PAK4), has demonstrated preclinical anti-tumor activity." (PMID 40854914, 2025). "Our recent work in immunocompetent syngeneic mouse model has shown that PAK1 or PAK4 knockout enhances vascular normalisation and anti-tumour immunity." (PMID 41228228, 2025).
tumor (continued). "Although PF-3758309 was initially developed as a PAK4 inhibitor, which plays an essential role in oncogenic signaling pathways, our results demonstrate that its anti-tumor effects extend beyond PAK4 inhibition." (PMID 40854914, 2025). "Together, these findings highlight the distinct mechanisms by which PAK1 and PAK4 regulate tumour growth, vasculature, and hypoxia." (PMID 41294859, 2025). "PAK4 assumes a critical role in mediating immune cell infiltration, where inadequate infiltration is a significant contributor to tumor resistance against therapies." (PMID 40332759, 2025). "This study investigated the effects of PAK1 and PAK4 on tumour vasculature and therapeutic response in an immunocompromised mouse model." (PMID 41228228, 2025). "We have explored the effects of PAK1 and PAK4 on the tumour vasculature of PDA and its impact on the PAK-regulated tumour immune response in this study." (PMID 40943273, 2025). "The inhibition of PAK4 suppressed tumor growth by stimulating the infiltration of cytotoxic T cells and by sensitizing the tumor response to immune checkpoint inhibitors and to CAR-T immunotherapy." (PMID 39941877, 2025). "Here, we used an immunocompromised SCID model to dissect immune-independent isoform-specific effects of PAK1 vs. PAK4 on tumour vasculature and gemcitabine response—focusing on tumour and vascular mechanisms without the interference of immune system effects." (PMID 41228228, 2025). "The proteomic data further confirmed the differential roles of PAK1 and PAK4 in regulating tumour vasculature." (PMID 41228228, 2025). "Our findings highlight the distinct roles of PAK1 and PAK4 in modulating the tumour vasculature and immune microenvironment in PDA." (PMID 40943273, 2025). "Despite evidence linking PAK signalling to immune regulation and vascular dynamics, the effects of PAK1 and PAK4 on tumour vasculature and chemotherapy response in PDA remain poorly defined." (PMID 41228228, 2025). "This was supported by proteomic profiles indicating the regulation of endothelial cell and leukocyte trans-endothelial migration in PAK1- or PAK4-knockout tumours." (PMID 40943273, 2025). "Additional studies are required to delineate specific NAD+ biosynthesis pathway and PAK4 localization to provide more mechanistic insights into the anti-tumor effects of KPT-9274." (PMID 38424218, 2024). "In an orthotopic tumorigenic model using nude mice, the overexpression of PAK4 significantly increased the in vivo tumor growth and pulmonary metastasis of KHOS/NP cells." (PMID 39273017, 2024). "In triple negative breast cancer cells, reducing Pak4 protein levels also prevented tumor cell growth." (PMID 38807162, 2024). "With regard the molecular mechanism of tumour promotion by PAK4, activation of the PI3K/Akt signalling pathway through Akt phosphorylation and activation of the ERK signalling pathway through MEK phosphorylation are critical." (PMID 38890401, 2024). "Recent studies have highlighted that PAK4 regulates multiple pathways to sustain tumor cell malignancy and confers drug resistance." (PMID 38238316, 2024). "PAK4 knockout induced adhesion protein re-expression in EC, inhibited tumor growth, improved T cell infiltration, and sensitized CAR-T cell immunotherapy." (PMID 38918817, 2024). "All four clusters of proteins had different protein expression levels between PAK4 KO and WT tumours at one week, and these differences were reduced in clusters 1, 2 and 4 at four weeks." (PMID 38797819, 2024). "Differentially expressed phospho-sites between WT and PAK4 KO tumours were demonstrated at one and four weeks." (PMID 38797819, 2024). "This analysis revealed a noteworthy upregulation in the expression levels of SNRNP200 and downregulation of UCHL1 and PAK4 proteins in the CPTAC tumor samples compared to normal samples." (PMID 39199615, 2024).